YBX1 (Y-box binding protein 1)
Diseases named in the same sentence as YBX1 in open-access papers (continued):
Sharing a sentence is not in itself a finding about the gene and the disease.
cancer (continued). "Analysis of a recently published large-scale proteome dataset covering 375 cell lines of the Cancer Cell Line Encyclopedia for CSP-family expression showed that YBX1 and CARHSP1 are specifically overexpressed in hematologic malignancies." (PMID 34465866, 2022). "Cold shock protein YBX1 has been identified as a pan-cancer dependency in publicly available CRISPR-Cas9-screens and several studies in different tumor entities." (PMID 34465866, 2022). "As for fusion-positive EVs, miRNA implicated in cancer, inflammation, connective tissue diseases, and angiogenesis have found to be increased (MDM2, CDKN1A, CDKN2A, IGF1R, SOX2, YBX1, BRINP3)." (PMID 35454972, 2022). "Taking together, our results suggest that HOTAIR is able to regulate the proliferation of cancer cells by modulating YBX1 nuclear localization, promoting in turn PCK2 and PDGFRB expression." (PMID 34266873, 2021). "Of the 90 pairs of CRC tissues, the expression of YBX1 was higher in cancer tissues than in adjacent non-cancer tissues, and YBX1 was positively expressed with NRF2." (PMID 34079797, 2021). "At the post-transcriptional level this tsRNAs group inhibited the expression of the YBX-1 transcript, changed the stability of oncogene mRNA, affected the expression of oncogene, and finally induced changes in the phenotype of the cancer cells." (PMID 34907180, 2021). "Using this system and complementary experimental techniques, we additionally found that HOTAIR regulates cancer cell proliferation at least partially via interacting with YBX1, altering its subcellular localization and target gene transcription." (PMID 34266873, 2021). "YBX1 is a multifunctional molecule that can regulate DNA and RNA expression, impacting the progression of several cancer types." (PMID 34079797, 2021). "Many studies indicate that the Y-box-binding protein-1 (YB-1) transcription factor can function as an oncoprotein to regulate stemness, drug-resistance and tumorigenic properties in various cancers including CRC." (PMID 33451103, 2021). "Among them, YBX1 attracted the attention of our research group, due to its well-known tumor-promoting role in many cancers." (PMID 34131399, 2021). "tRFs compete with carcinogenic transcripts such as EIF4G1, ITGB4, and AKT1 to bind the RNA-binding protein YBX1 in order to regulate the stability of tumour gene transcripts and inhibit the proliferation and metastasis of cancer cells." (PMID 34341710, 2021). "Critically, YBX1 is considered to be an oncoprotein that is up-regulated in many malignant cancers, promotes malignant transformation (proliferation, invasion, metastasis) and angiogenesis of various cancers as well as genomic instability." (PMID 34131399, 2021). "Considering its pivotal role in RNA regulated cancer biology, YBX1 was selected for further functional studies." (PMID 34266873, 2021). "These tRFs can modulate the expressions of oncogenes via YBX1 and ultimately inhibit cancer metastasis." (PMID 34934044, 2021). "Contrarily, tRFs produced during cancer compete with the oncogene transcripts to bind with YBX1 and thus suppress cancer cell growth." (PMID 34513302, 2021). "Previous studies have demonstrated that integrins bind YBX1 to mediate the activation of pro-survival signaling pathways in cancer cells." (PMID 34758833, 2021). "Y-box binding protein 1 (YB-1) is a multifunctional member of the cold-shock protein superfamily that plays an important role during development and cancer." (PMID 32882852, 2020). "In this regard, the YBX1 protein has been shown to be overexpressed in cancer cells resistant to cisplatin therapy, and in a recent study, YBX1 has been shown to mediate sensitivity to cisplatin in a xenograft model of NSCLC." (PMID 32708015, 2020). "Y-box binding protein-1 (YB-1) is a multifunctional oncoprotein that has been shown to regulate proliferation, invasion and metastasis in a variety of cancer types." (PMID 32823952, 2020).
cancer (continued). "DSCAM-AS1 can promote cancer progression by interacting with YBX1 and regulating expression of FOXA1 and ERα." (PMID 32929382, 2020). "The altered expression level of hub SFs has been reported in multiple types of cancer, such as YBX1, SART1, SNRPE, and SF3B4." (PMID 33101358, 2020). "As a master regulator of cancer cell biology, YBX1 is involved in all of Hanahan’s “hallmarks of cancer.”33,34 The YBX1 protein performs its functions both in the cytoplasm (as an RNA binding protein) and in the cell nucleus (as a transcription factor)." (PMID 33312753, 2020). "Collectively, these data suggest the significant role of methylation of YBX1 at R205 in mediating activation of a subset of NF-κB target genes with important roles in inflammation, cell survival and cancer." (PMID 32985589, 2020). "Decreased MIR22HG expression is associated with increased expression levels of MET and p21 oncogenes and cancer cell survival via its impact on YBX1 protein stability." (PMID 32760219, 2020). "Unsurprisingly, due to YBX1’s critical functions in the cell, its high expression has been identified in a multitude of cancers, including breast, colon, lung, ovarian, prostate, and thyroid cancer." (PMID 33375283, 2020). "The impact of phosphorylated PRMT5 and YBX1 on NF-κB signaling in cancer, amongst other regulators, underscores the relevance of phosphorylation in aiding tumor progression." (PMID 33375283, 2020). "Here, the authors discover the lncRNA lincNMR which is upregulated in cancer and drives cell proliferation by interacting with YBX1 and controlling nucleotide metabolism." (PMID 32587247, 2020). "This was particularly important as YBX1 is upregulated in many cancers and shows strong correlation with disease recurrence, chemotherapy resistance and relapse after chemotherapy." (PMID 32178290, 2020). "The multifunctional protein Y-box binding protein-1 (YB-1) regulates all the so far described cancer hallmarks including cell proliferation and survival." (PMID 33003386, 2020). "YBX1 is overexpressed in multiple cancers and regulates cell proliferation and survival, DNA replication and repair, multi-drug resistance and EMT." (PMID 32178290, 2020). "The multifunctional role of Ybx1 in different cellular processes to promote cancer progression is well established." (PMID 32792512, 2020). "YBX1 is subjected to post‐translational modifications, such as phosphorylation, ubiquitination, and acetylation, that tune the presence of the YBX1 in mRNPs and polysomes to regulate the translation of many genes involved in cancer." (PMID 33391635, 2020). "We then applied AmNA-ASO targeting Y-box binding protein-1 effectively as an antiangiogenic cancer therapy." (PMID 31110191, 2019). "Here, the authors identify 633 prognostic markers, 570 S-phase cancer-associated lncRNAs, and show SCAT7 regulates FGF/FGFR and PI3K/AKT/MAPK pathways via interaction with hnRNPK/YBX1 complexes." (PMID 29491376, 2018). "Among these transcription factors, YB-1 (Y-box-binding protein 1) commands a special concern in cancer progression." (PMID 29320405, 2018). "Mechanistic investigations on SCAT7 in multiple cancer types reveal that it interacts with hnRNPK/YBX1 complex and affects cancer cell hallmarks through the regulation of FGF/FGFR and its downstream PI3K/AKT and MAPK pathways." (PMID 29491376, 2018). "YBX1 plays diverse pro-oncogenic roles in cancers, such as malignant growth, invasion, metastasis, chemotherapy resistance and tumor angiogenesis." (PMID 29029484, 2017). "Here we showed that the expression of CDC25a had close relationship with the expression of YBX1 in cancer tissues samples on the basis of novel adenocarcinoma subtypes classification by immunohistochemical staining for the first time." (PMID 27384875, 2016). "High expression of YBX1 is frequently detected in a wide variety of cancers and closely relates to the progression and poor prognosis of these cancers." (PMID 26318844, 2015).
cancer (continued). "As YBX1 is a known oncogene, we further examined the expression levels of YBX1 in different types of cancers." (PMID 26318844, 2015). "Y-box binding protein 1 [YBX1] is a multifunctional protein known to facilitate many of the hallmarks of cancer." (PMID 26318844, 2015). "Elevated levels of YBX1 protein are highly correlated with cancer progression, making it an excellent marker in cancer." (PMID 26318844, 2015). "YBX1 promotes tumorigenesis, cell proliferation, replicative immortality, angiogenesis, invasion, and metastasis, most of which are the ‘hallmarks of cancer’ proposed by Hanahan and Weinberg." (PMID 26318844, 2015). "It is also now a widely accepted view that YBX1 is an oncoprotein that promotes the most of the famous ‘hallmarks of cancer’ proposed by Hanahan and Weinberg." (PMID 26318844, 2015). "Among them Y-box–binding protein-1 (YB-1) is a recently identified protein known to induce EMT in different cancers." (PMID 24770864, 2014). "Multidrug resistance of cancer cells acquired by MDR1 expression involves a transcriptional activity of Y-box binding protein 1 (YB-1)." (PMID 23983799, 2013). "We observed the post-transcriptional upregulation of YBX1/YB1 in rapidly growing CHO cells; this transcription factor is associated with cancer susceptibility and known to play a role in splice site selection." (PMID 23170974, 2012). "The described cancer biomarker Y-box-binding protein-1 (YB-1) is the focus of the present investigation." (PMID 22095225, 2011). "The literature concerning the subcellular location of Y-box binding protein 1 (YB-1), its abundance in normal and cancer tissues, and its prognostic significance is replete with inconsistencies." (PMID 21695211, 2011). "Previous studies described the relationship between YBX1 expression and/or nuclear localization of the protein, phenotypic properties of cancer cells and cancer patient survival." (PMID 21170361, 2010). "YBX1 is known to be involved in DNA repair, transcription, splicing, translation, and confers cisplatin resistance in several cancers." (PMID 20428086, 2010). "YBX1 transgene expression in mammary glands of lactating mice resulted in early onset of hyperplastic growth followed by progression to carcinomas." (PMID 21170361, 2010). "It was reported that YBX1 expression is required to maintain cancer cell proliferation." (PMID 40812419, 2025). "Ybx1 is a multifunctional RNA/DNA binding protein with broad roles in development and cancer but its role in ventral neural tube, floor plate or motor neuron development remains unknown." (PMID 41446274, 2025). "Clinically, targeting this complex could involve disrupting LINC02167/YBX1 or YBX1/ILF3 interactions to reduce the survival capacity of metastatic cancer cells, thereby enhancing the effectiveness of existing treatments." (PMID 40234937, 2025). "Overall, the aberrant upregulation of m5C readers like YBX1 in cancers creates a scenario in which any mRNA bearing m5C might be aberrantly stabilized, tilting the proteome toward a metastatic state." (PMID 41301491, 2025). "Remarkably, the oncogenes shown are Known to decrease apoptosis that could result in cancer cell survival like YBX1, SNRPE, RRM2, and COX6B1." (PMID 41347211, 2025). "The interaction between pleiotrophin (Ptn), nucleolin (Ncl), Y-box binding protein 1 (Ybx1), and stathmin 1 (Stmn1) in cancer cells forms a complex signaling pathway that influences critical cellular processes, including proliferation, migration, and epithelial-mesenchymal transition (EMT)." (PMID 39975141, 2025). "Oncoprotein Y-box-binding protein-1 (YB-1) is involved in all cancer hallmarks." (PMID 40420381, 2025). "LINC00857 interacts with YBX1, regulating apoptosis and autophagy in cancer cells." (PMID 40799245, 2025). "Additionally, YBX1 is frequently overexpressed in diverse cancers and correlates with poor prognosis, making it a clinically detectable biomarker and an ideal candidate for precision-targeted therapies." (PMID 41346602, 2025).
cancer (continued). "Overall, based on the protein levels, it appears that JMJD6 and YBX1 establish a feed-forward loop of expression that may augment their overlapping functions in cancer cells." (PMID 40855961, 2025). "While current research has established a strong correlation between the activity of YBX1 as a transcription factor and the progression of various malignant tumors, the precise mechanisms by which YBX1 operates in each tumor context remain incompletely understood." (PMID 40799245, 2025). "And we have determined LINC02418 could exert its cancer-promoting effects by interacting with YBX1 and enhancing YBX1 DNA-binding ability to the CTNNB1 promoter, which could induce the transcription of β-catenin and result in the activation of Wnt pathway." (PMID 40082414, 2025). "Upon further literature review, we identified YBX1 as a candidate RNA/DNA-binding protein that regulates the stability of target mRNAs, influencing processes such as apoptosis, proliferation, differentiation, and drug resistance in cancer." (PMID 40234937, 2025). "YBX1 is an oncogene which is consistently expressed in various types of cancers." (PMID 40593465, 2025). "Previous studies have indicated that YBX1 can activate PI3K–AKT pathway in various cancer cells." (PMID 40812419, 2025). "Interestingly, transcription factor MNX1 exhibits cytoplasmic localization characteristic in cancer cells and stabilizes PD‐L1 mRNA by interacting with Y‐box binding protein 1 (YBX1) and increasing YBX1 binding to PD‐L1 mRNA." (PMID 39912421, 2025). "The cellular viability of RASMCs was significantly decreased in shYbx1 samples, while the apoptotic level was significantly increased in shYbx1 samples, suggesting that Ybx1 knockdown repressed the growth and viability of RASMCs, which was consistent with previous results in cancer cells." (PMID 40045484, 2025). "Y-box binding protein-1 (YB-1), encoded by the YBX1 gene, is a multifunctional oncoprotein linked with many hallmarks of cancer, such as invasion and metastasis, hypoxic response, and increased chemoresistance in various cancers." (PMID 40149313, 2025). "And YBX1 could interact with lncRNA DSCAM-AS1 to disrupt the role of SE in inactivating the FOXA1 transcription network in cancer." (PMID 40790233, 2025). "Similarly, miR-216a and miR-137 bind to YBX1 mRNA, promoting its degradation and inhibiting YBX1 expression, thereby impacting cell proliferation, invasion, and chemosensitivity in different cancers." (PMID 40799245, 2025). "In the realm of YBX1 functional studies, a range of drugs and inhibitors have been identified to impact YBX1 activity and its regulatory network, offering a novel approach to cancer treatment." (PMID 40799245, 2025). "In addition, our group recently reported that YBX1 localizes to the mitochondrial inner membrane space in specific cancer cells, where it binds to mitochondrial pyruvate carrier (MPC), thereby inhibiting pyruvate uptake to promote cell metastasis." (PMID 40812419, 2025). "Combining YBX1-targeted drugs with immune checkpoint blockade may present a promising approach to enhance the effectiveness of cancer treatment." (PMID 38255791, 2024). "Around 2013, formulations targeting YBX1 were developed and tested for cancer treatment." (PMID 39727969, 2024). "Moreover, independent studies have shed light on various other specific aspects of YBX1’s involvement in cancer development." (PMID 38255791, 2024). "Furthermore, emerging evidence suggests a potential link between YBX1 and phenotypic plasticity in cancer." (PMID 38255791, 2024). "Studying YBX1 interactions with other key cancer-related proteins could identify novel drug targets beyond YBX1 itself." (PMID 38255791, 2024). "Addressing these obstacles is imperative in optimizing YBX1-targeted therapy for cancer treatment." (PMID 38255791, 2024).
cancer (continued). "YBX1 was reported to be overexpressed in a number of cancers, including liver cancer, breast cancer, and bladder urothelial cancer, and it may be a clinical biomarker for prognosis." (PMID 38238581, 2024). "YBX1 is also known as an oncoprotein that is overexpressed in numerous different types of cancer." (PMID 38254206, 2024). "The importance of YBX1 in cancer treatment is becoming increasingly recognized." (PMID 39727969, 2024). "YBX1, as a transcription factor, plays an important role in regulating genes in cancer." (PMID 39043648, 2024). "Therefore, future research on YBX1 in cancer should consider these contextual factors to reconcile the seemingly contradictory findings." (PMID 38255791, 2024). "It is crucial to decipher the precise mechanisms through which YBX1 influences the inflammatory milieu within tumors as this knowledge could offer valuable insights into cancer progression and potential therapeutic strategies." (PMID 38255791, 2024). "Moreover, studies have investigated the role of YBX1 in regulating metastasis-related processes in various cancers." (PMID 38255791, 2024). "YBX1’s ubiquitous expression and prominent role in oncogenesis and stress responses make it a critical focus in cancer biology, while YBX3’s more specialized functions in neuronal and muscle tissues underscore its importance in tissue-specific regulatory mechanisms." (PMID 39727969, 2024). "In addition to formulations targeting YBX1, there are clinical trials investigating cancer therapies that focus on YBX1." (PMID 39727969, 2024). "Given the known it can active MAPK pathway in a varies of cancers, and also acted as an oncogene in ES, we suspected that YBX1 might be a crucial target gene of SETD8 in ES." (PMID 38987564, 2024). "Based on this, we proposed YBX1 as a potential target for cancer treatment." (PMID 38255791, 2024). "Collectively, our findings suggest that APE1 and YBX1 may serve as potential targets in future therapeutic strategies for cancer and other SG-related diseases." (PMID 38436697, 2024). "This could involve tailoring therapy based on the individual cancer’s dependence on YBX1’s oncogenic or tumor-suppressive functions." (PMID 38255791, 2024). "Initially, YBX1 was found to transcriptionally activate the expressions of ABCB1, an ATP-binding cassette transporter associated with multidrug resistance, as well as the growth factor receptor genes EGFR and HER2/ErbB2 in cancer cells." (PMID 38254206, 2024). "However, further studies are needed to fully understand the molecular mechanisms responsible for the accelerated cell destruction by YBX1 and to elaborate the potential of adenovirus-based gene therapy for cancer treatment." (PMID 38255791, 2024). "Moreover, considering YBX1’s diverse roles in various biological processes, it is essential for research in YBX1-targeted cancer treatment to proceed thoughtfully." (PMID 38255791, 2024). "YBX1 has predictive value for drug resistance and poor prognosis in more than 20 cancer types, and upregulates the expression of multiple drug resistance genes, including ABCB1, MVP/LRP, TOP2A, CD44, CD49f, BCL2, and MYC, upon UV irradiation or Cisplatin treatment." (PMID 39168971, 2024). "Moreover, acting as a transcription regulator, YBX1 mediates cell proliferation, invasion, and metastasis by upregulating the transcription of specific genes in different cancer contexts." (PMID 38255791, 2024). "Targeting YBX1 may significantly enhance patient prognosis and quality of life by improving the effectiveness of cancer therapies." (PMID 39727969, 2024). "circRNA-SORE is transmitted to specific sensitive cells, which can prevent the breakdown of YBX1, a key cancer protein catalyzed by PRP19, and then inhibit the activation of related downstream factors (e.g., AKT, Raf1, ERK, etc.), thus spreading the resistance generated by chemotherapeutic drugs." (PMID 39530097, 2024).